FAP (fibroblast activation protein alpha)
Diseases named in the same sentence as FAP in open-access papers (continued):
Sharing a sentence is not in itself a finding about the gene and the disease.
tumor (continued). "Endopeptidase activity, unique to FAP, cleaves Gly-Pro-X sequences in denatured proteins such as collagen types I and III, aiding extracellular matrix (ECM) remodelling, tumour invasion, and fibrosis." (PMID 40741380, 2025). "Furthermore, FAP inhibition resulted in a strong immune-evasive phenotype of the co-cultured CAFs by increasing the frequency of myCAFs and lowering the number of apCAFs, which has a significant impact on the activation and infiltration of immune cells into the tumor." (PMID 41233863, 2025). "A noteworthy fact is that FAP is over-expressed in a high percentage of epithelial tumours, making FAPI-based radiopharmaceuticals pan-tumour markers as has been demonstrated." (PMID 40069442, 2025). "Inhibition of FAPα prevents the degradation of collagen and other components of the ECM, reducing opportunities for invasion and migration of tumor cells." (PMID 40918451, 2025). "The in vivo persistence of FAP/IL-15 CAR-T cells was evaluated on days 7, 14, and 28 post-treatment by detecting CD3 expression in spleen and tumor tissues using flow cytometry." (PMID 41455698, 2025). "FAP, a cell surface serine protease, is involved in ECM remodeling and promotes tumor growth and immune evasion." (PMID 40746533, 2025). "Under hypoxia and oxidative stress, tumor cells secrete TGF-β, IL-6, and platelet-derived growth factor (PDGF), activating CAF precursors, which upregulate fibroblast activation protein (FAP)." (PMID 40963620, 2025). "FAP-2286, a promising DOTA-pseudopeptide targeting the tumor microenvironment, has demonstrated superior tumor retention compared to quinoline-based analogs, making it an attractive theranostic agent." (PMID 40766056, 2025). "In agreement with the FAP-mediated reduction of the ECM integrity, a strong positive correlation between FAP and CD8+ T cells was found on tumor stroma (p = 0.0329)." (PMID 41233863, 2025). "To address challenges inherent in co-administering IL-15 with CAR-T cells targeting the tumor microenvironment, we developed a novel CAR construct that incorporates intrinsic IL-15 secretion capacity directly into FAP-targeted CAR-T cells." (PMID 41455698, 2025). "FAP inhibitors or FAP-CAR-T cells can further modulate the tumour stroma, allowing for improved access of effector T cells to the tumour core." (PMID 40624498, 2025). "Upon exposure to these tumor‐derived signals, MSCs differentiate into CAFs, acquiring specific characteristics, such as elevated expression levels of α‐SMA, FAP, and vimentin." (PMID 40656546, 2025). "Next to the myofibroblastic characteristics with increased levels of CD29 and αSMA upon FAP inhibition, a differential increase of ECM-myCAFs underscores the nuanced roles that these subpopulations play within the tumor stroma." (PMID 41233863, 2025). "FAP inhibitors (FAPIs) bind to FAP, and a FAPI labeled with Gallium-68 (68Ga) is a novel radiotracer with high tumor selectivity." (PMID 41301015, 2025). "Collectively, these results suggest that FAP+ CAF secretes lactate via MCT4, leading to lower infiltration of CD8-positive T cells and accelerated tumor progression." (PMID 40855046, 2025). "OMTX705, a humanized anti-FAP ADC, induced complete tumor growth inhibition and durable regression in patient-derived xenograft models, both as monotherapy and in combination with chemotherapy." (PMID 41441395, 2025). "MyCAFs are characterized by high expression of α-SMA, fibroblast activation protein (FAP), and collagen I, and play a critical role in ECM remodeling, tumor invasion, and resistance." (PMID 41383634, 2025). "The recently developed aluminum-[18F]-labeled 1,4,7-triazacyclononane-N,N′,N′′-triacetic acid-conjugated FAP inhibitor 04 ([18F]AlF-NOTA-FAPI-04) effectively visualizes various primary tumors and quantitatively assesses tumor involvement in cancer patients." (PMID 40777126, 2025). "FAP, CD29, αSMA, PDPN and CD90 were all upregulated in tumour fibroblasts, while FSP1 was more highly expressed in NCL fibroblasts." (PMID 38582812, 2024).
tumor (continued). "In summary, FAP+ CAFs play a pivotal role in the TME, contributing to tumor barrier formation, angiogenesis, and direct tumor cell regulation, albeit with possible preferences for specific cancer subtypes." (PMID 39239526, 2024). "NIR-PIT targeting CD25 was also used to deplete immunosuppressive Treg cells within the tumor, while NIR-PIT targeting FAP has been used to deplete in vitro stimulated CAFs from the TME." (PMID 38275890, 2024). "FAP-positive CAFs and α-SMA-positive CAFs can regulate both tumor-related pathways and Treg accumulation." (PMID 38352864, 2024). "The insights gathered from FAP+CAF prevalence, immune infiltration, and gene signatures provide valuable perspectives on tumor microenvironments, aiding in future research and clinical strategy development." (PMID 39035007, 2024). "Taken together, the human/murine cross-reactive FAP-CAR T cells were powerfully potent in killing human and murine FAP-positive tumor cells and CAFs." (PMID 39086477, 2024). "Through cytokine pathway profiling, we explored the relationship between FAP+CAF density and immune cell states, uncovering potential immunosuppressive circuits that limit anti-tumor activity in tumor-resident immune cells." (PMID 39035007, 2024). "As a tumor vaccine, eNVs‐FAP, which suppresses tumor growth by inducing a strong and specific CTL immune response directed against tumor cells and FAPCAF, as well as reprogramming immunosuppressive TMEs in models of colon, melanoma, lung, and breast cancer." (PMID 39015555, 2024). "FAP+ U87 cells were engineered to express RFP, while FAP− U251 cells were engineered to express GFP, to allow monitoring of the mixed tumor cell populations." (PMID 38975278, 2024). "Our in vivo results reveal that the FSA and FSA-Fmed tumor models are sensitive to PD-1 ICB monotherapy, but limited synergy was achieved by combining ICB with FAP-targeted RLT." (PMID 39008063, 2024). "In HNSC cells, FAP overexpression activated the PI3K-Akt pathway, promoting tumor proliferation, migration, and invasion." (PMID 39055892, 2024). "Interesting to note is that in OSCC, pro-tumor M2 macrophages are the most prevalent immune cells around αSMA+, FSP1+, and FAP+ CAF-rich areas." (PMID 38966131, 2024). "QUESTION: Does a heterobivalent molecule that recognizes both FAP and SSTR2 demonstrate improved efficacy in tumor-targeting and in vivo pharmacokinetics compared with those of its corresponding monomers?" (PMID 38176714, 2024). "Recent studies have highlighted the role of FAP in the TME, where it not only contributes to ECM remodeling but also influences tumor growth, invasion, and immune evasion." (PMID 39335703, 2024). "These PSMA/FAP dual-targeted radioligands enable imaging of lesions expressing FAP, PSMA, or both on the tumor cell surface or within the tumor microenvironment." (PMID 38773975, 2024). "Cancers with FAP-positive CAFs in their TME grow rapidly and FAP-targeted NIR-PIT not only suppresses their growth but improves tumor immunosuppression." (PMID 38555315, 2024). "Previously, we synthesized and evaluated two novel 68Ga-labeled pyridine-based FAP-targeted tracers, [68Ga]Ga-AV02053 and [68Ga]Ga-AV02070, and compared their binding affinity and tumor uptake to those of [68Ga]Ga-FAPI-04." (PMID 38398552, 2024). "Tumour cores were stained with PanCK to identify tumour regions and the fibroblast markers FAP, PDPN, αSMA, FSP1 and CD90 were used to identify the key CAF subsets predominant in tumour tissue: CAF-S1, CAF-S4 and CAF-S5." (PMID 38582812, 2024). "With the recent success of FAP-targeted imaging agents, targeting the ubiquitous presence of FAP in the TME has become a practical approach to design and develop radiotheranostic agents for efficacious pan-tumor diagnosis and treatment." (PMID 39766079, 2024).
tumor (continued). "For FAP, when the corresponding spots were mapped to the tissue, their distribution was concentrated at the tumor cell-depleted region where the PSMA density is lower and FAP density is higher than in the abundant region." (PMID 39629134, 2024). "The three subsets identified as more prevalent in the tumour (CAF-S1, CAF-S4 and CAF-S5) were investigated by staining for CAF markers FAP, αSMA, PDPN, CD90 and FSP1 in a cohort of 163 patients that were part of a TMA." (PMID 38582812, 2024). "Since FAP had a trend of lower expression at the tumor cell-abundant region than in the depleted region, it showed resistance to RPT in tumor cell-enriched regions." (PMID 39629134, 2024). "FAP-transduced fibroblast cells mixed with cancer cells have been treated with NIR-PIT, resulting in tumor growth inhibition." (PMID 38275890, 2024). "Specific markers are required to detect CAFs in tumours, including smooth muscle actin (α-SMA), fibroblast activation protein (FAP), fibroblast-specific protein 1 (FSP1), andplatelet-derived growth factor receptor-α/β (PDGFRα or PDGFRβ)." (PMID 38397199, 2024). "Immunohistochemical analysis of human ESCC tissues showed a positive correlation between the intensity of AREG expression at the tumor-invasive front and the expression level of the CAF marker FAP." (PMID 39451251, 2024). "In fact, a promising new FAP-targeting CAR-T cell has been shown to loosen the desmoplasia that restricts T cell invasion into tumors, which enables other tumor-targeting CAR-T cells to be used to finish the job and shrink the tumor." (PMID 38279300, 2024). "Results showed that our FAP-CAR T cells were powerfully potent in killing human and murine FAP-positive tumor cells and CAFs in multiple types of tumors in BALB/c and C57BL/6 mice and in patient-derived xenografts (PDX) model." (PMID 39086477, 2024). "We observed a high blood uptake (5–12 %ID/g at 1 h post-injection) in a mouse model with decreased tumor uptake in comparison to the 68Ga-labeled monospecific counterparts, PSMA-targeted [68Ga]Ga-HTK03041 and FAP-targeted [68Ga]Ga-FAPI-04." (PMID 38398552, 2024). "But when FAP− target cells were mixed with FAP+ target cells and incubated with FAP‐CAR‐T cells, significant killing of the FAP− tumor cells was observed." (PMID 38975278, 2024). "The current evidence for FAP-targeted RLT is derived only from case series and proof-of-concept studies in various tumor entities." (PMID 38540204, 2024). "Nevertheless, this study validated the therapeutic potential of pretargeting FAP sdAb TRT, with tumor growth delay and prolonged survival for the cohort treated with the highest injected activity." (PMID 39266288, 2024). "In murine FAP-positive tumor models, [68Ga]Ga-PNT6555 demonstrated selectivity for FAP-expressing tumors and reached high tumor-to-background contrast in PET imaging." (PMID 39765634, 2024). "These proteins synergize under FAP's regulatory scope to complexly modulate ECM dynamics, thereby supporting an aggressive tumor phenotype and facilitating cancer dissemination." (PMID 38826849, 2024). "Flow cytometry showed an increase in the frequency of CD8 T cells after anti-FAP NIR-PIT for both LL/2 and MMTV-PyVT tumor models." (PMID 38275890, 2024). "FAP-α knockdown reversed EMT and stopped the tumor invasion and pulmonary metastasis induced by TGF-β1-activated CAFs." (PMID 38455762, 2024). "The functional consequences of FAP+CAF-immune cell interactions are likely context-dependent, influenced by various factors such as tumor type and immunogenicity, stage, and the host immune status." (PMID 39035007, 2024). "For the present study, we also considered the catalytically inactive form of FAP (FAP_S624A), as inactive FAP was also reported to be activating the PI3K pathway for tumor proliferation." (PMID 39579201, 2024).
tumor (continued). "Given the encouraging in vitro results and our prior success with FAP targeting of PC3 and U87MG tumor-bearing mice, we proceeded to in vivo evaluation using the same tumor models." (PMID 38999044, 2024). "Digital image analysis to segment tumor regions (as tumor, stroma, necrosis, muscle, skin, or slide glass) was performed on H&E-stained scanned sections of MMTV-PyVT untreated control and anti-FAP NIR-PIT treatment groups using a random forest classifier." (PMID 38275890, 2024). "FAP is also being tested as a target to direct CAR-T cells and other immunotherapy agents to tumor tissue." (PMID 38562556, 2024). "Finally, we revealed that abundant FAP+ fibroblasts in advanced PCa and neuroendocrine PCa (NE) may promote Treg differentiation, further creating an immunosuppressive microenvironment that, in turn, helps tumor cells escape immune surveillance." (PMID 38483933, 2024). "FAP+ CAFs had the strongest spatial co-localization with DAB2+ TAMs in HCC, and DAB2+ TAMs had the highest proportion among all macrophages at the tumor border slides." (PMID 39239526, 2024). "Eight distinct CAF markers (αSMA, collagen-1, caveolin-1, CD140β, FAP, integrin α11, FSP-1 and CD90) were optimized during this study and validated on five HNSCC tumor samples." (PMID 38803925, 2024). "While most tumor types showed similar FAP+CAF levels, RCC metastatic samples (n=73) displayed significantly higher FAP+CAF density compared to primary (n=53) tumors." (PMID 39035007, 2024). "From our data in bone marrow chimeras using FAP-TK recipients or donors, depletion of FAP+ stromal cells and FAP+ hematopoietic cells by GCV together had a substantial suppressive tumor effect greater than the effect of either alone." (PMID 38275890, 2024). "Immuno-suppressive and immuno-permissive ECT comprise specific FAP+ CAF clusters and immune populations located at various distances from tumor aggregates and blood vessels." (PMID 38561380, 2024). "Inhibiting the endopeptidase activity of FAP, results in the prevention of ECM remodeling, necessary for tumor growth." (PMID 39579201, 2024). "There was a marked upregulation of CXCR4 and FAP in the tumor tissues of TNBC patients, suggesting that they promote tumor progression in a concerted manner." (PMID 38587644, 2024). "For example, in a highly desmoplastic preclinical pancreatic ductal adenocarcinoma (PDAC) model, CAR-T cell targeting of FAP+ CAFs removes the physical and immunosuppressive CAF barrier, and enhances tumor infiltration of other T cell subsets." (PMID 38413223, 2024). "engineered bispecific CAR-T cells targeting both fibroblast activation protein (FAP) and GPC3 simultaneously to address tumor diversity in HCC." (PMID 39569202, 2024). "The results showed significantly decreased levels of FAP‐α, α‐SMA, and collagen I in the tumor spheres after JQ1 treatment." (PMID 38417121, 2024). "In mice treated with FAP‐CAR‐T cells, both the GFP and RFP signals in necropsied tumor tissues were significantly reduced compared to tumors in either control group, suggesting CAR‐T cell targeting of both FAP+ U87‐RFP and FAP− U251‐GFP cells." (PMID 38975278, 2024). "along with reduced tumor growth and decreased expression of perivascular CAF activation markers (e.g., ACTA2, PDGFRβ, FAP)." (PMID 38453816, 2024). "This study demonstrated the feasibility and efficacy of 68Ga-FAPI-LM3, a divalent molecule for PET imaging of FAP and SSTR2, emphasizing its clinical utility for tumor detection and staging in patients with NPC." (PMID 38176714, 2024). "Fibroblasts in the presence of UPP1-overexpressing tumor cells displayed a higher CAF score and increased expression of CAF markers such as FAP and MMP11." (PMID 38331898, 2024). "Results show increased expression of SLC1A5 and FAP by flow cytometry and confocal imaging, and CD163 (confocal imaging) in HCC827 tumor slices incubated with REVs or when co-cultured with HCC827-GR tumor slices." (PMID 39431017, 2024).
tumor (continued). "The fibroblasts also expressed collagen-1 and FAP-α, and whole transcriptomic analysis (WTA) showed abundant ECM- and EMT-related expression in heterospheroids, thus reflecting a representative tumor-like microenvironment." (PMID 39011470, 2024). "Results showed that the FAP-CAR T cells were powerfully potent in killing human and murine FAP-positive tumor cells and CAFs, and were biologically safe and exhibited low-level OTOT, warranting further clinical investigation into our FAP-CAR T cells." (PMID 39086477, 2024). "Histological sections of both tumor and adjacent normal samples from these patients were evaluated for the expression of the CAF markers THY1, αSMA, TAGLN, FAP, PDPN, and MMP2." (PMID 39335130, 2024). "This suggests that the expression of FAP and DAB2 genes is valuable in indicating the prognosis of tumor patients." (PMID 39239526, 2024). "A DNA-barcoded micellular system (DMS) functionalized with CAFs-targeting anti-FAP antibodies (antiCAFs-DMS) can selectively inhibit PIN1 in CAFs, leading to efficacious but transient tumor growth inhibition." (PMID 38892190, 2024). "During follow-up using [68Ga]Ga-FAP-2286-PET/CT and tumor markers, disease progression occurred, leading to a change of treatment to a FOLFOX scheme as a second-line therapy." (PMID 39338305, 2024). "CALB2 was overexpressed in tumor stromal CAFs, where the mean density of IHC showed a strong positive correlation between CALB2 and fibroblast activation protein (FAP)." (PMID 39358777, 2024). "Clusters within FAP+ CAF subpopulation were identified across several tumor types, and the inter-tumor and inter-patient heterogeneity was proven." (PMID 38540204, 2024). "By using FAPI-46 as a sub-efficacious FAP-RLT modality, due to its short tumor retention and fast clearance, we investigated the importance of essential parameters like target expression and tumor radiation dose for (FAP-)RLT efficacy." (PMID 39008063, 2024). "We checked the basal expression of two important CAF-specific markers, FAP and α-SMA, both frequently upregulated in ovarian CAFs isolated from patients’ tumor specimens." (PMID 38891879, 2024). "Seven days after radiation, [18F]FAPI PET/CT imaging showed that the tumor proliferation was inhibited and showed a weak [18F]FAPI signal in LLC tumors and lungs, which was consistent with FAP-α staining in LLC tumors." (PMID 38407800, 2024). "We demonstrate that anti-FAP NIR-PIT can effectively deplete endogenous CAFs in the TME, induce anti-tumor effector cell activation and IFN-γ production, and suppress tumor growth." (PMID 38275890, 2024). "CAFs can arise from normal fibroblasts that are directly activated by cytokines secreted by tumor cells, such as TGF-β1 and PDGF-BB, and express specific markers, including α-SMA, FAP, and PDGFR-β." (PMID 38169376, 2024). "It is even more critical in the context of FAP TRT, a hot topic in nuclear medicine, in which quinoline-based FAPIs showed limited responses because of their fast tumor clearance." (PMID 39266288, 2024). "For control purposes, the in vivo performance of [68Ga]Ga-TATE-46 was investigated in MC38 tumor-bearing mice, which exhibit low expression of SSTR2 and FAP." (PMID 39770488, 2024). "CAFs, which generally originate from activated fibroblasts within the tumour microenvironment, overexpress a specific subset of biomarkers, such as α‐SMA, FAP‐α and PDGFR‐α/β, according to the tumour type." (PMID 38766687, 2024). "Understanding the molecular and cellular impact of FAP-radioligands on CAF, tumor cells, and immune cells is crucial, particularly when targeting FAP+ CAF alone." (PMID 38540204, 2024). "In CRC, spatial transcriptomics revealed that FAP+ fibroblasts and SPP1+ macrophages colocalized in the tumor tissues and surrounded the tumor epithelial cells, which implies that there was a potential interaction between the two." (PMID 39858416, 2024).